NTHL1 (nth like DNA glycosylase 1)
Diseases named in the same sentence as NTHL1 in open-access papers (continued):
Sharing a sentence is not in itself a finding about the gene and the disease.
familial adenomatous polyposis 3 (5 papers, 2021 to 2024). "Biallelic NTHL1 pathogenic variants are associated with Familial adenomatous polyposis 3, an autosomal recessive inherited disorder." (PMID 39144255, 2024). "On the other hand, homozygous or compound heterozygous PVs in NTHL1 have been linked to Familial adenomatous polyposis - 3 (MIM: 616415) and most recently a multi-tumour phenotype." (PMID 36969007, 2023). "Biallelic mutations in NTHL1 are responsible for familial adenomatous polyposis-3 (FAP3)." (PMID 34026625, 2021).
breast tumors (3 papers, 2021 to 2025). "We were able to evaluate the breast tumours of the patients with the NTHL1 c.244C>T variant further in the Helsinki and Tampere BC series." (PMID 38036545, 2023).
ovarian carcinoma (3 papers, 2021 to 2023). A malignant neoplasm originating from the surface ovarian epithelium. "The (c.268C>T; p.(Gln90*)) stop-gain variant in the NTHL1 gene was identified in a woman (IV-3) with ovarian cancer (62 years)." (PMID 34026625, 2021).
colon cancer (2 papers, 2023). "The importance of this question is underscored by observations that high-risk factors for colon cancer include biallelic mutations of 2 base excision repair genes, NTHL1, and hMYH." (PMID 37738679, 2023). "Alleles mapping in human orthologs RAD18 and NTHL1, increase the risk of colon cancer." (PMID 37738679, 2023). "Considering that human orthologs NTHL1 and RAD18 are risk factors for colon cancer, our results provoke further studies suggesting that polymorphic NTHL1 alleles may confer HAA sensitivities." (PMID 37738679, 2023).
colorectal adenoma (2 papers, 2013 to 2019). An adenoma that arises from the colon or rectum. "We observed statistically significant associations between colorectal adenoma risk and polymorphisms in the FEN1 gene (two tagSNPs) and NTHL1 gene (one tagSNP) among Asian-Pacific Islanders, and the APEX1 gene among African-Americans (one tagSNP)." (PMID 23951112, 2013). "However, among Asian-Pacific Islanders we observed two SNPs in FEN1 and one in NTHL1, and among African-Americans one SNP in APEX1 that were associated with colorectal adenoma risk." (PMID 23951112, 2013).
colorectal tumor (2 papers, 2020 to 2024). "Thirteen colorectal tumors from NTHL1 LoF carriers underwent WES." (PMID 32860789, 2020).
endometrial cancer (2 papers, 2023 to 2024). Primary or metastatic malignant neoplasm involving the endometrium (mucous membrane that lines the endometrial cavity). "Although the contribution of the SBS30 in endometrial cancer of patient #7 is somewhat lower compared to the CRCs of the pathogenic NTHL1 biallelic variant carriers, it remains the predominant observed signature in this tumor in spite of being evaluated in a different tumor type." (PMID 37727376, 2023).
acute myocardial infarction (1 paper, 2025). Necrosis of the myocardium, as a result of interruption of the blood supply to the area. "NTHL1, primarily known for its role in DNA repair, has also been identified alongside eight other m5C readers as part of a specific m5C modification signature used to detect early acute myocardial infarction." (PMID 41030849, 2025).
basal-cell skin cancer (1 paper, 2023). "Biallelic pathogenic variants in the NTHL1 gene cause a high-penetrance multi-tumour syndrome, which is especially manifested with colorectal, breast, endometrial, urothelial, and basal-cell skin cancer, as well as meningeal tumours." (PMID 38036545, 2023). "Furthermore, the results suggested a high risk of colorectal, urinary tract, and basal-cell skin cancer for homozygous individuals, supporting NTHL1 as a recessive multi-tumour susceptibility gene." (PMID 38036545, 2023). "Besides BC, homozygous NTHL1 c.244C>T significantly associated with a high risk of CRC (OR = 168 [24.4–1152], P = 1.9 × 10–7) and basal-cell skin cancer (OR = 66.0 [6.02–723], P = 6.0 × 10–4)." (PMID 38036545, 2023).
bladder tumors (1 paper, 2023). "According to the COSMIC catalog, SBS5 was found to be increased in bladder tumors with mutations in the DNA excision repair gene ERCC2, whereas signature SBS30 was found to be related to a deficiency in base excision repair due to inactivating mutations in NTHL1." (PMID 37906280, 2023).
endometrial tumor (1 paper, 2021). "Tumor mutational signatures provided evidence that germline variation in BRCA1, PALB2, RAD51C, MUTYH and NTHL1 can be (but is not always) associated with tumor mutational signatures consistent with a functional role of these genes in endometrial tumor development." (PMID 33917078, 2021).
gastric tumors (1 paper, 2020). "Mislocalization of NTHL1 to the cytoplasm as well as single nucleotide polymorphisms (SNPs) in the promoter region of NTHL1, resulting in decreased expression, have been linked to the etiology of a subset of human gastric tumors." (PMID 32595826, 2020).
gastrointestinal stromal tumor (1 paper, 2022). "In this second case, we present a patient with a heterozygous NTHL1 mutation who developed a gastrointestinal stromal tumor, pilocytic astrocytoma, tall cell papillary thyroid cancer, invasive ductal papilloma, spinal nerve sheath tumors, and spinal hemangiomas." (PMID 35967160, 2022).
Hepatic hemangioma (1 paper, 2021). A congenital vascular malformation in the liver composed of masses of blood vessels that are atypical or irregular in arrangement and size. "We present the case of a 22-year-old patient with a heterozygous NTHL1 variant who developed an arm schwannoma, spinal schwannoma, and hepatic hemangioma." (PMID 34367820, 2021).
melanoma (1 paper, 2025). A malignant, usually aggressive tumor composed of atypical, neoplastic melanocytes. "The results showed upregulation of NR1H3, NTHL1, and SNX1, and downregulation of DSP in melanoma compared to normal skin." (PMID 41573564, 2025).
Multiple Endocrine Neoplasia syndromes (1 paper, 2019). "Beyond Multiple Endocrine Neoplasia syndromes, however, we report the first cases of patients with a PALB2, an APC and a NTHL1 pathogenic variants and both malignancies." (PMID 31592449, 2019).
pancreatic adenocarcinoma (1 paper, 2025). "There is little literature regarding NTHL1 gene expression in pancreatic adenocarcinoma and may represent a further source of investigation in this setting." (PMID 39786582, 2025).
serrated polyposis (1 paper, 2019). "The aim of our study is to elucidate the role of NTHL1 in the predisposition to personal or familial history of multiple tumor types, familial/early-onset nonpolyposis CRC, and serrated polyposis." (PMID 31227763, 2019).
cancer (43 papers, 2017 to 2025). A tumor composed of atypical neoplastic, often pleomorphic cells that invade other tissues. "Patients with germline mutations of DNA damage repair genes (BRCA1, BRCA2, or NTHL1) had a later evolutionary onset of dissemination than patients with triple-proficient cancers (P = 0.03 by Wilcoxon’s test)." (PMID 38175731, 2024). "The current study is a comprehensive cancer risk analysis for NTHL1 in an extensive case–control material." (PMID 38036545, 2023). "Summarizing, we concluded that the NTHL1-related cancer predisposition in Poland occurs in 1/150,000 newborns each year." (PMID 37834005, 2023). "Nevertheless, because of the high cancer risk, we suggest that NTHL1 should be included in cancer gene panels in clinical diagnostics, at least for the most common tumour types reported in the patients with pathogenic biallelic NTHL1 variants." (PMID 38036545, 2023). "We obtained the data for recessive risk association analyses from FinnGen for all malignant tumour types diagnosed in the individuals homozygous for the NTHL1 c.244C>T variant." (PMID 38036545, 2023). "In conclusion, our results indicate that biallelic LoF variants in the NTHL1 gene cause a high risk of multiple cancer types, including BC." (PMID 38036545, 2023). "Homozygous mutations to NTHL1 are known to increase cancer risk, particularly in the colon and breast." (PMID 35967160, 2022). "Eight patients harbored monoallelic variants in high/moderate penetrance cancer genes associated with autosomal dominant inheritance and a second variant in a gene associated with a recessive disorder (MUTYH, FANCA, NTHL1) or low penetrance cancer (TYR)." (PMID 36132150, 2022). "The patient was additionally diagnosed with carcinomas of multiple organs characteristic of the tumor spectrum of NTHL1-associated polyposis." (PMID 36387175, 2022). "Genomic instability and HRD were measured using genome-wide copy number data from the NTHL1 associated cancers." (PMID 33980861, 2021). "While the increased cancer risk is established for individuals with biallelic NTHL1 pathogenic variants, the risk estimates for heterozygous carriers are unclear." (PMID 32949222, 2020). "NTHL1 mutational screening was performed in 312 cancer patients with personal or family history of multiple tumor types, 488 with hereditary nonpolyposis CRC, and 96 with serrated/hyperplastic polyposis." (PMID 31227763, 2019). "Single-knockout mice deficient for Neil1 and Nthl1 are phenotypically inconspicuous, the combined knockout, however, is highly cancer prone, indicative of mutual compensation of both factors for oxidative DNA damage repair." (PMID 31566562, 2019). "Despite the lack of published evidence, similar responses may be expected for NTHL1-deficient cancers." (PMID 40237887, 2025). "The signature of base excision repair deficiency was clonal in all samples from the patient with a germline NTHL1 mutation, and the phenotype was maintained among subclonal mutations, strongly supporting its involvement in the development and progression of this cancer." (PMID 38175731, 2024). "Additionally, the susceptibility to multiple tumour types should be considered in surveillance and cancer-prevention strategies for the individuals with biallelic variants, and clinical practice guidelines should be developed for the NTHL1 gene." (PMID 38036545, 2023). "Still, due to the rarity of homozygous individuals, the observed effect sizes for the increased recessive risk associated with the c.244C>T variant, here, are uncertain and the CIs are wide, and the NTHL1 gene warrants further evaluation for more precise risk estimates for different cancer types." (PMID 38036545, 2023). "Since then, the name “NTHL1 syndrome” has been proposed for this multi-cancer predisposition." (PMID 37834005, 2023). "Here, we show that heterozygous NTHL1 mutations may increase cancer risk and may even manifest similarly to NTS." (PMID 35967160, 2022).
cancer (continued). "Moreover, mutational signatures have been associated with cancer predisposition genes (e.g., NTHL1 in multiple cancer types, including breast cancer), and used to stratify cancer patients for precision treatment." (PMID 35377867, 2022). "Little is known about the cancer risk in patients who have heterozygous NTHL1 mutations." (PMID 35967160, 2022). "Notably, two of these patients harbored heterozygous alterations in cancer predisposing genes associated with autosomal recessive cancer predisposition syndromes (NTHL1 and MSH3)." (PMID 33466343, 2021). "To examine the cancer risks for the heterozygous carriers, we retrieved the results for additive risk association analyses from FinnGen for the available malignant tumour types, which have been diagnosed in the patients with biallelic NTHL1 variants in the FinnGen data or reported previously." (PMID 38036545, 2023). "In a pan-cancer analysis of 11,081 patients, 39 were heterozygous for NTHL1 PVs, which was similar to the frequency observed in gnomAD non-Finnish European controls." (PMID 40237887, 2025). "Detecting heterozygous PVs in the MUTYH, NTHL1, MSH3, and MBD4 genes poses a clinical challenge for counseling monoallelic carriers about their cancer risk and for establishing rational surveillance protocols." (PMID 40237887, 2025). "The signature correlating mostly with the age of cancer diagnosis (SBS1-like) and NTHL1 deficiency-related signature (SBS30-like) predominately contributed to the mutation spectrum of EAC tumors regardless of race." (PMID 38637560, 2024). "In the current study, we examined the risks for the heterozygous carriers to malignant tumours, which have been detected in the patients with biallelic NTHL1 variants." (PMID 38036545, 2023). "In our cohort, fourteen patients harbored a monoallelic P/LPV associated with recessive disorders (NTHL1, RECQL4, ERCC3, FANCA, and BLM) and one patient harbored PV in a low penetrance cancer gene (TYR)." (PMID 36132150, 2022). "Based on these analyses, the evidence for NTHL1 p.Q90* segregating with cancer within these families remains uncertain." (PMID 32949222, 2020). "MUTYH and NTHL1 defects are associated with increased risk for cancer, and C:G→A:T transversions and C:G→T:A transitions are respectively associated with MUTYH- and NTHL1-related tumors." (PMID 33339161, 2020). "Finally, we propose that NTHL1 should be included in cancer gene panels in clinical diagnostics and clinical practice guidelines should be developed for cancer screening strategies for individuals with pathogenic biallelic NTHL1 variants." (PMID 38036545, 2023). "Ten individuals with the homozygous NTHL1 c.244C>T variant were identified in the FinnGen study: nine of them had been diagnosed with one or multiple tumour types as verified by the Finnish Cancer Registry, and one had no cancer diagnosis." (PMID 38036545, 2023). "Identifying a carrier of NTHL1 c.224C>T; p.Gln82Ter was not surprising given the frequency of carriers of this variant = 0.002 in the non-cancer non-Finnish European population in gnomAD v2.1.1." (PMID 36969007, 2023). "Monoallelic NTHL1 variants are unlikely to cause a substantially increased risk of cancer if any8,12,25,27." (PMID 38036545, 2023). "NTHL1 had a predominantly nuclear localization in both wild-type and NTHL1-het cancers." (PMID 33980861, 2021). "Unlike other cancer predisposing syndromes, all variants reported in NTHL1 biallelic carriers are stop-gain, frameshift or canonical splice-site variants; no missense variants have been yet identified as cause of the disease (data obtained October 2020)." (PMID 33806975, 2021). "Family history of cancer of the identified heterozygous NTHL1 p.Q90* (c.268C>T)a carriers." (PMID 32949222, 2020).
cancer (continued). "Previously, only four reported biallelic NTHL1 variant carriers have been described without malignant neoplasms, raising the number to six out of 32 patients without any malignant neoplasms when including the siblings." (PMID 31645984, 2019). "As other cancer types have been described in patients with homozygous nonsense variants in NTHL1, a gastroscopy and a dermatological examination were performed, finding no suspicious results." (PMID 31645984, 2019). "Moreover, only two cancers had the SBS30 mutational signature: a serous ovarian carcinoma with LOH of the NTHL1 wildtype allele, and a prostate cancer without evidence of LOH." (PMID 40237887, 2025). "For example, mice lacking both OGG1 and MYH or NEIL1 and NTHL1 show strong cancer susceptibility." (PMID 28665322, 2017). "Among the 36 NTHL1 biallelic carriers, 29 (80.6%) were diagnosed with CRC and/or another type of cancer at a median age of 47 years (range: 24–67) at first diagnosis and 18 of them (62.1%) showed an early age of onset (<50 years)." (PMID 33806975, 2021). "Importantly, this study further underscores the importance for investigations into germline mutations in NTHL1 and other BER proteins in order to identify mutations that increase the risk for cellular transformation and may lead to increased cancer incidence in humans harboring these mutations." (PMID 32595826, 2020). "In addation, CAT, POLE, NTHL1, ATP7B, ISCA2, NDUFA1 and NDUFB2 have also been reported to play a key role in the development of cancers." (PMID 36685880, 2022). "The 12.2% de novo germline mutation rate in MMR genes and other non-CRC cancer susceptibility genes (BRCA1, BLM, and NTHL1) reported herein for the young sporadic CRC group is reasonable and expectable." (PMID 33260537, 2020). "Identification of biallelic MUTYH or biallelic NTHL1 cases may facilitate prevention of non-CRC cancers through screening or prophylactic surgery." (PMID 39793275, 2025). "The mouse mutants individually lacking OGG1, NTHL1, NEIL1, NEIL2, or MYH or cells derived from these mutants are viable and do not develop a strong phenotype, such as accelerated aging or enhanced incidence of spontaneous cancer." (PMID 28665322, 2017).